EIF3M (eukaryotic translation initiation factor 3 subunit M)
Diseases named in the same sentence as EIF3M in open-access papers:
EIF3M is named in the same sentence as 21 diseases in open-access papers, as found by Europe PMC text mining. Sharing a sentence is not in itself a finding about the gene and the disease. The quoted sentences say what the papers report.
breast carcinoma (3 papers, 2020 to 2024). "The expression of eIF3m, one of the 13 subunits of m6A reader eIF3, positively correlates with the development and progression of breast cancer." (PMID 33292526, 2020). "After selection of suitable breast cancer cell lines with higher eIF3m expression, stable transfected cells with eIF3m knockdown were constructed for investigating the significance of eIF3m in vitro and exploring the potential pathogenesis of TNBC tumorigenesis." (PMID 32368187, 2020). "Conversely, eIF3m promotes breast cancer cell migration and invasion by activating EMT." (PMID 33292526, 2020). "Downregulation of eIF3m inhibits breast cancer proliferation and increases the rate of apoptosis." (PMID 33292526, 2020). "Overexpression of eIF3m has been observed in TNBC but not in non-TNBC or normal breast tissues and it reduces overall survival (OS), relapse-free survival, and post-progression survival in breast cancer patients." (PMID 33292526, 2020).
glioma (3 papers, 2019 to 2021). A benign or malignant brain and spinal cord tumor that arises from glial cells (astrocytes, oligodendrocytes, ependymal cells). "Recently, systematically profiling found that the expression of eIF3b, eIF3i, eIF3k, and eIF3m was increased with the glioma grade and poorer overall survival." (PMID 32565801, 2020). "The results indicated that the expression levels of eIF3a, eIF3b, eIF3i, eIF3k, eIF3l and eIF3m were significantly (P < 0.05) correlated to the OS of glioma patients in both datasets." (PMID 31171919, 2019). "Regarding the eIF3 complex, significantly higher protein expression in gliomas compared to CCBT was detected for eIF3B (III: p < 0.05), eIF3D (I: p < 0.05; III: p < 0.05), eIF3H (III: p < 0.05), eIF3I (I: p < 0.05, III: p < 0.001, IV: p < 0.01) and eIF3M (III: p < 0.01)." (PMID 33807050, 2021).
hepatocellular carcinoma (2 papers, 2021 to 2025). A malignant tumor that arises from hepatocytes. "In hepatocellular carcinoma models, EIF3M modulated tumor proliferation, migration, and activated oncogenic pathways like Wnt/β-catenin." (PMID 41341921, 2025). "The experimental results demonstrated that EIF3M overexpression significantly enhanced the proliferative capacity of hepatocellular carcinoma cells, while EIF3M knockdown resulted in a marked reduction in tumor cell proliferation." (PMID 41341921, 2025). "In vitro experiments in hepatocellular carcinoma models demonstrated that EIF3M critically regulates malignant cell behaviors." (PMID 41341921, 2025). "Finally, we used HCC cell lines for in vitro functional validation, determining how EIF3M expression modulates malignant phenotypic behaviors in hepatocellular carcinoma." (PMID 41341921, 2025).
triple-negative breast carcinoma (2 papers, 2020 to 2025). An invasive breast carcinoma which is negative for expression of estrogen receptor (ER), progesterone receptor (PR), and human epidermal growth factor receptor 2 (HER2). "Similar investigations have also revealed that EIF3M exhibits overexpression in prostate cancer and triple-negative breast cancer, with cellular experiments confirming significant growth inhibition in tumor cells following EIF3M knockdown." (PMID 41341921, 2025).
astrocytoma (1 paper, 2021). "Besides the already known eIFs, we demonstrated significantly elevated protein levels of eIF3D, eIF3H, eIF3I, eIF3M, p-eIF4G, eIF4H, eIF5 and eIF6 in astrocytoma tissue compared to CCBT." (PMID 33807050, 2021).
colon cancer (1 paper, 2018). "EIF3M binds to tumor-associated genes in human colon cancer cell lines, which in turn affects cell proliferation, cell cycleand cell apoptosis." (PMID 29532746, 2018).
ductal breast carcinoma (1 paper, 2020). "normal samples revealed that eIF3m was significantly elevated in invasive breast carcinoma, such as invasive ductal breast carcinoma, mixed lobular and ductal breast carcinoma, invasive lobular breast carcinoma, and so on." (PMID 32368187, 2020).
liver failure (1 paper, 2020). A liver disease characterized by the liver losing or has lost all of its function. "Deep knockdown of Eif3m also resulted in the decrease of translation and liver failure after 2–3 weeks." (PMID 32968084, 2020).
ovarian carcinoma (1 paper, 2021). A malignant neoplasm originating from the surface ovarian epithelium. "In this paper, we identified the potential gene with prognosis-related AS event in ovarian carcinomas (the multiple genes presented in the network), and EIF3M, RPS27A, SNRNP200 and UBR4 were found at the core of gene interaction network." (PMID 34001978, 2021). "Secondly, we identified more accurate and reliable hub genes including EIF3M, RPS27A, SNRNP200 and UBR4, and we also performed an enrichment analysis to characterize the role of AS in ovarian cancer." (PMID 34001978, 2021).
tumor (10 papers, 2018 to 2025). "Firstly, through multi-dimensional data validation, we have confirmed the potential association between EIF3M expression patterns and malignant tumor phenotypes, providing critical targets for subsequent functional verification." (PMID 41341921, 2025). "The expression of eIF3b, eIF3i, eIF3k and eIF3m was increased with the tumor grade, and was associated with poorer overall survival [All Hazard ratio (HR) > 1 and P < 0.05]." (PMID 31171919, 2019). "To explore evidence supporting EIF3M as a novel tumor diagnostic marker and prognostic predictor, we conducted an exploration and discussion by systematically analyzing the correlation between EIF3M expression levels and tumor Stage." (PMID 41341921, 2025). "This approach aims to more comprehensively evaluate the differential expression patterns of EIF3M across diverse tumor entities." (PMID 41341921, 2025). "To elucidate the functional role of EIF3M in tumor progression, we assessed the regulatory effects of its dysregulated expression on the core biological behaviors of tumor cells." (PMID 41341921, 2025). "We also observed that EIF3M expression was significantly downregulated in tumor tissues of KICH, PCPG, THCA, and UCEC." (PMID 41341921, 2025). "Functional experiments using these models have confirmed that EIF3M significantly promotes tumor cell proliferation and migration." (PMID 41341921, 2025). "For instance, single-cell analysis revealed that the oncogenic genes HS2ST1 and EIF3M are primarily expressed in tumor cells, while the protective gene PPP3CA is mainly expressed in immune cells." (PMID 40951342, 2025). "These complex findings suggest that during tumor progression, genomic instability drives spatiotemporal fluctuations in EIF3M expression levels, which are dynamically regulated through multilayered networks to adapt to the tumor microenvironment." (PMID 41341921, 2025). "These discoveries not only expand the functional understanding of the eukaryotic translation initiation factor family in tumor biology but also highlight the translational medical significance of EIF3M as a potential therapeutic target." (PMID 41341921, 2025). "The results revealed that in KIRP, LIHC, and LUAD, EIF3M expression levels exhibited a positive correlation trend with tumor Stage, whereas EIF3M expression was significantly lower in advanced-stage SKCM patients compared to early-stage cases." (PMID 41341921, 2025). "In most cancer types, EIF3M expression is negatively correlated with these targeting miRNAs, which is consistent with its significant overexpression in tumor tissues compared to normal counterparts." (PMID 41341921, 2025). "Through integrated analysis of multi-omics data, we identified a significant correlation between EIF3M expression dysregulation and tumor progression, suggesting its functional involvement in this process." (PMID 41341921, 2025). "EIF3M was overexpressed in multiple cancers and correlated with advanced tumor stage and poor survival." (PMID 41341921, 2025). "Difference is found in the expression of EIF3A, EIF3B, EIF3D, EIF3F, EIF3H, EIF3J, and EIF3M in different tumor stages." (PMID 36051357, 2022). "In silico, increased gene expression over all four tumor grades was determined for eIF3B, eIF3I, eIF3K and eIF3M." (PMID 33807050, 2021). "Recently, eukaryotic translation initiation factor 3 m (eIF3m) has been declared to be involved in the malignant progression of various neoplasms." (PMID 32368187, 2020). "When eIF3m was up-regulated, more oncogenes were expressed and vital signaling pathways related to tumor growth and invasion were activated." (PMID 32368187, 2020). "Furthermore, using HCC cell line models, this study demonstrated that differential EIF3M expression levels markedly influence tumor cell behaviors, including proliferation and migration." (PMID 41341921, 2025).
tumor (continued). "In-depth analysis revealed that patients harboring EIF3M alterations exhibited significantly higher tumor mutational burden (TMB) levels compared to those without EIF3M alterations." (PMID 41341921, 2025). "Additionally, we explored the relationship between EIF3M expression levels and remodeling of the tumor microenvironment." (PMID 41341921, 2025). "However, in LAML and PCPG, EIF3M expression displayed the opposite trend, showing significantly lower levels in tumor tissues compared to normal tissues." (PMID 41341921, 2025). "HS2ST1 and EIF3M likely influence the tumor immune microenvironment by inhibiting NK cell function, whereas PPP3CA may exert protective effects by promoting the infiltration of specific immune cells." (PMID 40951342, 2025). "Levels of nine eIF3 subunits involving eIF3A, eIF3B, eIF3C, eIF3D, eIF3E, eIF3H, eIF3I, eIF3J, and eIF3M were significantly increased in cancer tissues, whereas the eIF3L expression level in tumours was independently decreased than that of normal tissues (p < 0.05)." (PMID 31885740, 2019). "Except EIF3E and EIF3F found down-regulated and conferred tumor suppressive activity in cancers, majority of EIF3 members including EIF3A, EIF3B, EIF3C, EIF3D, EIF3H, EIF3I and EIF3M were up-regulated and played important roles in tumor progression of multiple cancer types." (PMID 29568350, 2018). "EIF3M expression was closely associated with poor patient prognosis, including reduced OS and DFS, as well as key biological processes such as genetic mutations, TMB, DNA methylation, miRNA regulatory networks, and remodeling of the tumor immune microenvironment." (PMID 41341921, 2025). "This included for example for bendamustine EIF3M involved in cell proliferation, cell cycle progression and cell death, SMAD3 involved in epithelial-to-mesenchymal transition, tumor suppressor and metastasis formation, and UBXN1 influencing EGFR signaling." (PMID 41146244, 2025). "In KIRP, LIHC, and LUAD, higher tumor stages demonstrated a significant positive correlation with elevated EIF3M expression levels, while in SKCM, an opposing negative correlation trend was observed." (PMID 41341921, 2025). "HS2ST1 and EIF3M were predominantly expressed in tumor cells, while PPP3CA was mainly expressed in non-tumor cells, such as immune cells." (PMID 40951342, 2025).
cancer (8 papers, 2018 to 2025). A tumor composed of atypical neoplastic, often pleomorphic cells that invade other tissues. "The EIF3M exhibits heterogeneous mutation frequencies across different cancer types: its highest mutation rate is observed in BRAC (6.64%), predominantly driven by Amplification (6.16%) with a minor contribution from Mutations (0.47%)." (PMID 41341921, 2025). "Pan-cancer analysis of disease-free survival (DFS) revealed that elevated EIF3M expression was significantly associated with shortened DFS in patients with ACC, LUAD, and PAAD." (PMID 41341921, 2025). "After screening cancer types with ≥3 statistically significant survival indicators, we identified that high EIF3M expression in ACC and LUAD was significantly associated with poor patient prognosis." (PMID 41341921, 2025). "The integrated analysis of expression-prognosis correlation patterns confirms that differential EIF3M expression serves as a pan-cancer diagnostic and prognostic biomarker." (PMID 41341921, 2025). "However, the regulatory mechanisms governing EIF3M’s dysregulated expression in cancer and its associated biological functions remain poorly understood, necessitating further in-depth investigation." (PMID 41341921, 2025). "Expression changes of EIF3M across cancers and their prognostic associations." (PMID 41341921, 2025). "Furthermore, we investigated the correlations between EIF3M mutations, epigenetic regulation, and tumorigenesis, while revealing the underlying mechanisms of cancer progression mediated through regulatory networks driven by interacting genes and miRNAs." (PMID 41341921, 2025). "Our pan-cancer TMB analysis identified a significant correlation between EIF3M expression levels and TMB status in 12 malignancies." (PMID 41341921, 2025). "In extended analyses, we systematically evaluated the DNA methylation profiles of EIF3M across pan-cancer cohorts, unveiling its epigenetic regulatory landscape." (PMID 41341921, 2025). "Through analysis, it has been observed that EIF3M exhibits significant expression abnormalities across multiple malignant tumor types." (PMID 41341921, 2025). "We utilized publicly available databases to perform a comprehensive bioinformatics analysis of EIF3M’s biological roles in oncogenesis, aiming to elucidate its pan-cancer expression patterns and prognostic significance." (PMID 41341921, 2025). "Initially, we conducted a preliminary analysis of the expression levels of EIF3M in pan-cancer using the TIMER2.0 database based on TCGA data." (PMID 41341921, 2025). "In this study, it was observed that high expression of EIF3M is accompanied by significantly elevated levels of MDSCs across nearly all cancer types." (PMID 41341921, 2025). "CpG methylation analysis of the EIF3M revealed significant differences in methylation levels between 13 cancer types and normal tissues." (PMID 41341921, 2025). "This study aims to systematically dissect the multidimensional molecular characteristics and clinical significance of EIF3M in pan-cancer contexts." (PMID 41341921, 2025). "In most cancer types, EIF3M exhibits hypomethylation patterns relative to normal tissues, and this epigenetic alteration correlates with its consistent overexpression observed in tumors." (PMID 41341921, 2025). "This study systematically analyzed the expression profile of EIF3M in pan-cancer tissues and revealed its significant overexpression in multiple malignancies such as LIHC, COAD, and LUAD." (PMID 41341921, 2025). "Pan-cancer genomic analysis revealed that the EIF3M exhibits frequent genomic alterations across 15 major malignancies, with BRCA, COAD, and HNSC showing particularly high mutational rates." (PMID 41341921, 2025). "Collectively, our findings highlight EIF3M’s value as a promising pan-cancer biomarker worthy of further investigation for its utility in prognosis prediction and as an indicator of immunotherapeutic response." (PMID 41341921, 2025).
cancer (continued). "Eukaryotic translation initiation factor 3 subunit M (EIF3M) was strongly downregulated in all groups, with only carcinoma luminal B to 0.734." (PMID 39000458, 2024). "Inconsistent with its cancer-promoting role, K-M Plotter demonstrated that higher transcriptional levels of EIF3M led to better RFS (particularly those classified as grade III)." (PMID 35040374, 2022). "To systematically evaluate the biological significance of EIF3M in prognosis across multiple cancer types, we performed survival curve analysis using the GEPIA2 database to investigate the clinical relevance between its expression levels and patient survival outcomes." (PMID 41341921, 2025). "Next, these three filtered core miRNAs were imported into the ENCORI platform to further investigate whether their expression patterns are correlated with EIF3M across pan-cancer contexts." (PMID 41341921, 2025). "To further validate the expression characteristics of EIF3M at the post-transcriptional regulatory level, we systematically evaluated the protein-level expression patterns of EIF3M across multiple cancer types on the GEPIA2 platform using proteomics data from the CPTAC database." (PMID 41341921, 2025). "Finally, to comprehensively characterize the transcriptional and regulatory networks of EIF3M in pan-cancer, we systematically integrated multi-dimensional omics data from the TCGA database for gene activity scoring analysis of EIF3M." (PMID 41341921, 2025). "Firstly, utilizing the cBioPortal analysis platform, select pan-cancer whole genome data from TCGA and the International Cancer Genome Consortium (ICGC) to construct the genetic alteration profile of EIF3M." (PMID 41341921, 2025). "We also observed a significant correlation between EIF3M expression levels and PFS in patients with various malignant tumors." (PMID 41341921, 2025). "In lung cancer research, investigators have identified that EIF3M interacts with genes including SAAL1 and CAPRIN1 to promote tumorigenesis and cancer progression." (PMID 41341921, 2025). "It should be noted that although this study has preliminarily validated the functional roles of EIF3M in regulating malignant phenotypes in HCC through in vitro models, its cross-cancer applicability still requires confirmation through systematic functional genomic studies." (PMID 41341921, 2025). "Our pan-cancer analysis identified three miRNAs that target EIF3M and show a significant negative correlation with its expression." (PMID 41341921, 2025).
EIF3M also shares sentences with these, for which no sentence is quoted: gastric cancer (1 paper); Hypertension (1); infection (1); invasive breast carcinoma (1); invasive ductal breast carcinoma (1); invasive lobular breast carcinoma (1); lung carcinoma (1); preeclampsia (1); prostate carcinoma (1); virus infection (1).